CD1E (CD1e molecule)
Description:
T-cell surface glycoprotein CD1e, soluble binds diacetylated lipids, including phosphatidyl inositides and diacylated sulfoglycolipids, and is required for the presentation of glycolipid antigens on the cell surface. The membrane-associated form is not active.
Synonyms: R2
Tractability: Small molecule: it has a high-quality binding pocket. Antibody: UniProt predicts a signal peptide or a membrane-spanning region. PROTAC: UniProt records ubiquitination sites on it; ubiquitination databases record sites on it.
Gene: Protein-coding gene on chromosome 1 (158,353,696 to 158,357,553, forward strand). Ensembl gene ENSG00000158488.
Subcellular location: Golgi apparatus membrane (T-cell surface glycoprotein CD1e, membrane- associated); Early endosome; Late endosome; Lysosome lumen (T-cell surface glycoprotein CD1e, soluble)
Subcellular location (Human Protein Atlas): Golgi apparatus; Nucleoli
Gene Ontology:
Molecular function: endogenous lipid antigen binding; exogenous lipid antigen binding; lipopeptide binding
Biological process: antigen processing and presentation, endogenous lipid antigen via MHC class Ib; antigen processing and presentation, exogenous lipid antigen via MHC class Ib; immune response; positive regulation of T cell mediated cytotoxicity
Cellular component: Golgi apparatus; external side of plasma membrane; plasma membrane; early endosome; Golgi membrane; late endosome; lysosomal lumen
Genetic constraint (gnomAD): Loss-of-function variants: 53 observed, 43.92 expected, observed/expected ratio (o/e) 1.21, 90% interval 0.97 to 1.52. The upper end of that interval is the gene's LOEUF score, 1.52, which puts it in group 6 of 6, group 1 being the genes least tolerant of losing a copy. Missense variants: 492 observed, 493.47 expected, observed/expected ratio (o/e) 1, 90% interval 0.93 to 1.07. Synonymous variants: 189 observed, 188.07 expected, observed/expected ratio (o/e) 1, 90% interval 0.89 to 1.13.
Homologues: Orthologues: chimpanzee CD1E (97% identical), macaque CD1E (89% identical), guinea pig CD1E (65% identical), pig CD1E (61% identical), zebrafish mhc1lfa (17% identical), zebrafish si:dkey-52p2.5 (16% identical), zebrafish mhc1lja (16% identical), zebrafish mhc1lda (15% identical), zebrafish mhc1lla (15% identical), zebrafish mhc1lba (14% identical), zebrafish mhc1laa (14% identical), zebrafish mhc1lga (14% identical), and 1 more. Paralogues in human: CD1B (47% identical), CD1A (46% identical), CD1D (46% identical), CD1C (45% identical), HLA-A (22% identical), HLA-E (21% identical), HLA-F (21% identical), HLA-B (21% identical), HLA-C (20% identical), HLA-G (20% identical), AZGP1 (17% identical), HFE (17% identical), and 10 more.
Diseases named in the same sentence as CD1E in open-access papers:
CD1E is named in the same sentence as 12 diseases in open-access papers, as found by Europe PMC text mining. Sharing a sentence is not in itself a finding about the gene and the disease. The quoted sentences say what the papers report.
asthma (1 paper, 2020). "The CD1C, TLR7, PTK2, CD1E, CD1A, and ERBB2 genes had a higher rate of engaging protein interactions in the PPI for the moderate-to-severe asthma phenotype." (PMID 32512817, 2020).
Autoimmunity (1 paper, 2023). The occurrence of an immune reaction against the organism's own cells or tissues. "By operating a lipid and glycolipids antigen selection to be presented by other CD1 isoforms, CD1e might modulate both antimicrobial immune response and autoimmunity." (PMID 36851115, 2023).
breast carcinoma (1 paper, 2022). "For example, an ieQTL was associated with CD1E expression in ER + breast cancer only in low-purity tumors." (PMID 35725412, 2022).
diffuse large B-cell lymphoma (1 paper, 2023). "CD1E is one type of CD1 molecule that is expressed in dendritic cells, and it has been identified to be associated with diffuse large B-cell lymphoma patients’ long-term survival." (PMID 37426414, 2023).
psoriasis (1 paper, 2015). An autoimmune condition characterized by red, well-delineated plaques with silvery scales that are usually on the extensor surfaces and scalp. "Immune-related genes (e.g. CCL8, LCP2, CD1E) and IL-36G, which was recently associated with psoriasis pathogenesis, were increased in AD LS skin." (PMID 26459294, 2015).
tumor (7 papers, 2012 to 2024). "The CD1E gene encodes a protein involved in lipid antigen presentation and was expressed at higher levels in low-purity tumors suggesting that the gene is likely to be expressed in non-tumor cells." (PMID 35725412, 2022). "Subsequently, immunohistochemistry was used to detect the expression of STK11, Ki67, and CD1E in tumor tissues." (PMID 37506141, 2023). "It was revealed that STK11 mutation affected CD1E expression to regulate macrophage differentiation in LUAD and then promote tumor progression." (PMID 37506141, 2023). "Messenger RNA expression of CD1C and CD1E, a TCR contributory gene, was associated with T regulatory (Treg) cell infiltration (r > 0.35) and M2 macrophage (r > 0.43) tumour infiltration." (PMID 34664400, 2021). "Our results also suggested that, by downregulating CD1E, STK11 deficiency may inhibit the differentiation of M1 macrophages in LUAD and then promote tumor growth." (PMID 37506141, 2023). "The eight-gene-signature prognostic model (ANGPTL5, CD1B, CD1E, CNTFR, CTSG, EDN3, IL12B, and IL2)-based high- and low-risk groups were significantly related to overall survival (OS), tumor microenvironment (TME) immune cells, and clinical characteristics in LUAD." (PMID 34745015, 2021). "This study showed higher mRNA levels of MHC-I for tumours that will not relapse after treatment and tumours that will recur have lower expression of CD1c, CD1e and MCP-1." (PMID 22919375, 2012).
cancer (2 papers, 2015 to 2024). A tumor composed of atypical neoplastic, often pleomorphic cells that invade other tissues. "Our analysis also identified several antigen-presenting molecules as potential cancer drivers, including one class I (HLA-C), one class II (HLA-DRB1), and three HLA-like proteins (CD1C, CD1E and MR1)." (PMID 26485003, 2015).
CD1E also shares sentences with these, for which no sentence is quoted: infection (2 papers); COVID-19 (1); leukemia (1); lung adenocarcinoma (1); lung carcinoma (1).